ERG (ETS transcription factor ERG)
Diseases named in the same sentence as ERG in open-access papers (continued):
Sharing a sentence is not in itself a finding about the gene and the disease.
prostate carcinoma (continued). "Plays an oncogenic role in prostate cancer as the fusion gene with ERG, and has also been demonstrated to be essential for the cellular entry of severe acute respiratory syndrome coronaviruses (SARS-CoV)." (PMID 41244516, 2025). "Chromosomal deletions represent the next most common recurrent genomic alterations in prostate cancer after TMPRSS2:ERG fusions." (PMID 40554389, 2025). "This case illustrates a unique sequence in which COVID-19-related prostatitis was followed by the diagnosis of prostate cancer in a patient with a TMPRSS2::ERG gene fusion." (PMID 41267989, 2025). "Prostate cancer (PCa) can be classified into four distinct molecular subtypes based on IHC staining analysis of ERG and PTEN expression." (PMID 40165885, 2025). "A gene fusion between NDRG1 and ERG has been identified in prostate cancer, resulting in a chimeric protein in ERG overexpressed prostate cancer cells." (PMID 40862714, 2025). "Despite the high prevalence of ERG transcription factor translocations in prostate cancer, the mechanism of tumorigenicity remains poorly understood." (PMID 40858905, 2025). "ERG rearrangements are found in 40–50% of the prostate carcinomas, ETV1 rearrangements/overexpression in 8–10%, and rearrangements involving ETV4, ETV5, or FLI1 in 2–5% of the cases, being mutually exclusive." (PMID 40808640, 2025). "TMPRSS2 facilitates SARS-CoV-2 entry into host cells and is simultaneously one of the most frequent genomic drivers in prostate cancer through its fusion with ERG." (PMID 41267989, 2025). "ExoDx analyses exosomal RNA of three genes that are elevated in high-grade prostate cancer: ERG, PCA3 and SPDEF." (PMID 40115018, 2025). "CT/MRI-guided biopsy differentiates osteoblastic/osteolytic prostate cancer metastases, molecular markers (ERG fusion, RUNX2, Wnt dysregulation) indicate osteo-tropic mechanisms correlatable with imaging." (PMID 41458551, 2025). "The EWSR1-ETS Ewing loops appear to be less complex than TMPRSS2:ERG prostate cancer loops with fewer rearrangements (two to ten rearrangements in one or two loops)." (PMID 40332527, 2025). "ERG promoted nuclear localization of AEG-1/SND1, which promoted cell proliferation and the deletion of SND1-reduced tumor burden in an ERG-overexpressing mouse prostate cancer model." (PMID 40282551, 2025). "The prognostic significance of TMPRSS2: ERG fusions in prostate cancer has been debated since the identification of this alteration in the disease." (PMID 40332161, 2025). "Transcriptomic analysis of ERG+ human prostate cancers confirms the presence of rare ERG+ BasalLum cells, as well as IM cells whose presence is associated with a worse prognosis." (PMID 40858905, 2025). "The TMPRSS2::ERG fusion is one of the most frequent genomic alterations in prostate cancer and contributes to oncogenic transformation, particularly when combined with PTEN loss." (PMID 41267989, 2025). "Owing to its prevalence in prostate cancer (293 of 810 samples (36.2%)), ERG was the most frequent fusion driver gene identified in our cohort (295 of 11,091 samples (2.7%))." (PMID 40711866, 2025). "Multiple lines of evidence implicate translocations in ERG, which are present in ~40–50% of prostate cancers (PCa) in Western cohorts, as an initiating event in PCa." (PMID 40858905, 2025). "MiR-429 is a member of the miR-200 family (miR-141, miR-200a, miR-200b, and miR-200c) and was reported to target the ERG gene in prostate cancer and promote angiogenesis in hepatocellular carcinoma." (PMID 40862714, 2025).
prostate carcinoma (continued). "Analysis of CNA clonality has shown NKX3-1 deletion, RB1 deletion, FOXP1 deletion, and ERG rearrangement are the earliest forms of structural variation occurring in prostate cancer evolution." (PMID 40840524, 2025). "FT has additionally been associated with higher risk of ERG‐positive prostate cancers, which have an androgen‐induced fusion between the androgen‐regulated TMPRSS2 gene and the oncogene ERG." (PMID 38234143, 2024). "Among the new biomarkers is the TMPRSS2-ERG fusion gene, the most common (90% of all genes that fuse with ERG) genetic alteration seen in prostate cancer." (PMID 38730435, 2024). "Many of these proteins, including EWS:FLI1 and EWS:ERG fusions in Ewing sarcoma (EwS) and TMPRSS2:ERG in prostate cancer (PCa), drive oncogenic programs via binding to GGAA repeats." (PMID 38530366, 2024). "We also observed strong inhibition of other prostate cancer oncogenic signaling, including ERG and FOXA1, after CBPD-409 treatment." (PMID 38586029, 2024). "We explored the interplay between p300 and AR or ERG, which are the two most critical oncogenic transcription factors in prostate cancer cells, in AR-positive/ERG-positive VCaP cells." (PMID 38586029, 2024). "Studies have shown that the androgen signaling pathway plays a role in facilitating the formation of the TMPRSS2::ERG gene fusion, which is present in approximately 50% of prostate carcinomas." (PMID 39087020, 2024). "Prostein is the second most common 5′ partner gene in ETS Transcription Factor ERG (ERG) rearrangements in prostate cancer after Transmembrane Serine Protease 2 (TMPRSS2), another constitutively expressed androgen regulated gene in prostate epithelium." (PMID 38218896, 2024). "TMPRSS2:ERG gene fusion, which is reported to occur in between 20–80% of prostate cancer, leads to changes promoting EMT, as demonstrated in an in vitro prostate cancer model consisting of immortalised prostate epithelial cells in culture." (PMID 38730670, 2024). "In prostate cancer, an ERG gene fusion with the promoter region of the androgen-induced TMPRRSS2 gene is a common finding and is used as a diagnostic tool and a target for immunotherapy." (PMID 38933637, 2024). "Current research on ERG has predominantly focused on its role in prostate carcinoma and Ewing sarcoma." (PMID 38933637, 2024). "In a subgroup analysis of IHC-PSMA positive prostate carcinomas (PSMA%neg < 20%), an additional ERG positivity was significantly associated with lower SUVmax values in the corresponding PSMA PET scan (p = 0.033, Kruskal-Wallis test)." (PMID 39083067, 2024). "LncRNA-PCAT5 is a new oncogenic lncRNA in ERG-positive prostate cancer, which has the prospect of becoming a biomarker of prostate cancer and a new therapeutic target." (PMID 38565547, 2024). "The investigators focused their efforts on examining the effects of ERG, a transcription factor commonly overexpressed in prostate cancer." (PMID 38607014, 2024). "We further showed that degradation of these subunits, along with PBRM1, led to rapid and widespread chromatin compaction, perturbing essential oncogenic programs driven by transcription factors such as AR, FOXA1, and ERG in prostate cancer models." (PMID 38557192, 2024). "What this test does is read the levels of exosomal expression of the PCA3, SPDEF and ERG genes' RNAs to predict the possibility of higher‐grade prostate cancers in patients." (PMID 39410867, 2024). "The ETS family transcription factor ERG is frequently overexpressed in prostate cancer and known to have a role in carcinogenesis, however, the underlying mechanism is less understood." (PMID 37973913, 2023). "Investigating the clonal relationship between tumor foci in prostate cancer often involves immunohistochemical analyses of ERG and PTEN proteins." (PMID 38067216, 2023). "Previously, miR-145 and miR-196 expressions are shown to downregulate ERG expression in prostate cancer and leukemia, respectively." (PMID 37310937, 2023).
prostate carcinoma (continued). "By focusing on specific genes of interest, such as AR, PTEN, and ERG, known to impact prostate cancer progression and metastasis, we discovered novel regulatory interactions." (PMID 37686146, 2023). "A TMPRSS2:ERG translocation is detectable in ~50% of all prostate cancer foci, and results in overexpression of ERG (ETS Transcription Factor ERG) from exon 4 to 3′-end in >95% of TMPRSS2:ERG cases." (PMID 36765747, 2023). "Among enriched gene sets are those genes associated with cell cycle and proliferation (CHANG_CYCLING_GENES), prostate cancer tumorigenesis in human prostate cancer (TCGA_PrCa_UP), and ERG target genes in prostate cancer (VCAP_siERG_DN and VCAP_Lenti_ERG_UP)." (PMID 37018402, 2023). "TK216 is a derivative of YK-4-279, which is known to target EWS-FLI1-harboring Ewing sarcoma and ETV1- and ERG-driven prostate cancer." (PMID 37895265, 2023). "For instance, TMED3 was highly expressed in prostate cancer and metastatic prostate cancer, and high expression of TMED3 was associated with the expression of the androgen receptor and ERG oncogene." (PMID 36991473, 2023). "EVs isolated from the urine of prostate cancer patients have shown the presence of prostate cancer biomarkers, PCA-3 and TMPRSS2:ERG thus showing specific diagnostic and clinical value for the transcriptome within tumor EV." (PMID 37091854, 2023). "One potential explanation for the minimal phenotype is the low dosage level of achievable ETS (e.g., ERG or ETV1) proteins in previous ETS-driven murine prostate cancer models." (PMID 37018402, 2023). "In mice, prostate-specific Snd1 deletion reduces cancer growth and tumor burden in a prostate cancer model (PB-Cre/Ptenflox/flox/ERG mice), Moreover, we find a significant overlap between prostate transcriptional signatures of ERG and SND1." (PMID 37973913, 2023). "Most ETS gene fusions in prostate cancer bring the gene that is coding for ERG under a regulatory sequence controlled by androgens, resulting in de novo expression of this oncogenic transcription factor in prostate cancer cells." (PMID 37591798, 2023). "Overexpression of N-terminal truncated, but fully functional ERG due to ERG gene fusion with TMPRSS2 gene occurs in approximately 50% of prostate cancer (PCa) patients." (PMID 37537199, 2023). "As reported by various groups, the functional role of ERG is validated in various leukemia, Ewing sarcoma and prostate cancer." (PMID 36899924, 2023). "In this context, previous publications demonstrated that USP9x-dependent stabilization of insulin receptor substrate 2 or the transcription factors PBX homeobox 1 and ERG supported prostate cancer growth and metastasis." (PMID 37173959, 2023). "The association of ERG overexpression with specific histomorphologic features and prognosis in prostate cancer has been a topic of debate since the discovery of the TMPRSS2:ERG fusion." (PMID 37511059, 2023). "This study indicates that miR-4482 and -3912 can suppress the ERG expression and its target genes, thereby, halt prostate cancer progression." (PMID 37310937, 2023). "Based on these varied consequences of ERG overexpression, it is logical to use therapeutic agents that can target ERG in prostate cancer." (PMID 37310937, 2023). "This structural study provides additional evidence and mechanistic insight into CHD1’s roles in modulating AR signaling and ERG fusions during prostate cancer evolution." (PMID 36776288, 2023). "The authors also aimed to examine the prognostic importance of ERG expression in patients with prostate cancer who underwent surgical prostatectomy." (PMID 37511059, 2023). "In prostate cancer, several miRNAs regulate the ERG expression such as miR-9, miR-26, miR-182, miR-200b, and miR-221." (PMID 37310937, 2023). "Several studies tried to investigate the pathogenetic role of TMPRSS2:ERG fusion in carcinogenesis and the development of prostate cancer." (PMID 37511059, 2023).
prostate carcinoma (continued). "YK-4279 specifically inhibits ERG transcription and ERG-mediated cell migration and proliferation in prostate cancer." (PMID 37066790, 2023). "These oncogenic ETS factors have been detected in most prostate cancer resulting from the binding 5′untraslated segment of TMPRSS2 to ERG." (PMID 37112663, 2023). "A pilot study showed the presence of two known prostate cancer biomarkers, PCA-3 and TMPRSS2: ERG, in exosomes isolated from patients’ urine as a potential diagnosis and monitoring of prostate cancer patient status." (PMID 37456253, 2023). "Co-IP of PABPC1 using an anti-ERG antibody in TMPRSS2/ERG-positive VCaP prostate cancer cells demonstrated that endogenous ERG-bound PABPC1." (PMID 37956771, 2023). "The significance of broad imprinted gene upregulation in ERG-mediated prostate cancer will have to be investigated in the future studies." (PMID 37973913, 2023). "Gene rearrangements that increase ETS system activity contribute to cancer growth and development, including the fusion between TMPRSS2 and ERG, which is found in approximately 50% of prostate cancer cases." (PMID 37686423, 2023). "Prostate cancer patients can exhibit distinctive ERG gene fusions, resulting in the upregulation of ERG expression." (PMID 37894380, 2023). "We chose TMPRSS2:ERG fusion because this is the most frequent molecular alteration found in prostate cancer, and IHC data on AR expression because of its known interaction with PSAP." (PMID 37892063, 2023). "Studies have shown that the ERG fusion-positive–PTEN-negative prostate cancers display unfavorable disease outcomes such as earlier biochemical recurrence and cancer progression." (PMID 37185705, 2023). "For instance, a study on 46,719 males with prostate cancer reported that lycopene showed protective mechanisms against prostate cancer by inhibiting the fusion of TTSPs and ERG genes." (PMID 37823149, 2023). "The fusion of the promoter of TMPRSS2 with the coding region of ERG is the most prevalent molecular aberration in prostate cancer; it occurs in approximately 50% of prostate cancer cases and is the most common gene fusion in solid tumors." (PMID 37511059, 2023). "The most effective ERG O’PROTAC molecule ERG OP-C-N1 degraded ERG protein and inhibited cancer cell growth in vitro in prostate cancer VCaP cell line." (PMID 36986626, 2023). "Despite the fact that TMPRSS2:ERG fusion is a frequently occurring molecular event in prostate cancer, its precise impact on the clinical aspects of the disease remains controversial." (PMID 37511059, 2023). "More than half of prostate cancer cases have an ERG-TMPRSS2 (ETS-related gene—Transmembrane Protease Serine 2) fusion on chromosome 21." (PMID 37736898, 2023). "The TMPRSS2:ERG fusion, as one of the most common molecular aberrations in prostate cancer, has been extensively studied as a potential therapeutic target." (PMID 37511059, 2023). "Inhibiting HDAC3 reduces the growth of ERG-dependent leukemic and prostate cancer cells, indicating that the interaction between ERG and the NCoR-HDAC3 co-repressor complex is crucial for its oncogenic activity." (PMID 37735473, 2023). "This TMPRSS2:ERG fusion affects approximately half of all prostate cancers and predominates in patients of a younger age." (PMID 37892063, 2023). "Functional, genetic, and biochemical studies revealed that P199 contributes to the ERG-NCoR-HDAC3 interaction, thereby highlighting HDAC3 as a potential therapeutic target for ERG-mediated leukemias and, possibly, other malignancies such as prostate cancer." (PMID 37735473, 2023). "The molecular crosstalk between ERG and androgen receptor (AR) has implications in the complex network of prostate cancer signaling pathways." (PMID 37310937, 2023). "The single-cell RNA sequencing of the immune composition of TME revealed differences in CD4+ T cell proportion in prostate cancer types based on the presence of ERG-TMPRSS2 fusion." (PMID 37736898, 2023).
prostate carcinoma (continued). "The degraders successfully promoted the degradation of two oncogenic TFs, lymphoid enhancer-binding factor 1 (LEF1) and ETS-related gene (ERG), and showed suppressive effects in prostate cancer modes." (PMID 37480049, 2023). "For example, ERG-rearrangements possibly induce metabolic changes in prostate cancer by increasing glucose uptake through activation of major metabolic signaling molecules such as neuropeptide Y (NPY)." (PMID 37724906, 2023). "Further analysis depicted that the incidence of ERG fusion, the most common genomic modification in prostate cancer patients, was less frequent among Sardinians." (PMID 37112663, 2023). "The over-expression of ERG is highly attributed to the TMPRSS2: ERG fusion, a recurrent chromosomal rearrangement that represents the most common molecular alteration of prostate cancer, approximately occurring in one-half of the cases." (PMID 37185705, 2023). "For example, the prostate cancer fusion TMPRSS2::ERG, identified as our fourth most tumor-enriched fusion (182 of 465 TCGA prostate tumor samples), is also detected in six normal prostate samples (five TCGA and one GTEx)." (PMID 37323575, 2023). "The molecular mechanisms driving prostate cancer have been intensively investigated, and involve hormone-driven signalling pathways, “classical” oncogenes including ERG and MYC, and tumour suppressors like PTEN." (PMID 37752235, 2023). "Transcriptional changes in ERG rearrangement-positive prostate cancer cells promoted metabolic changes (e.g., glucose uptake increase) by activating signaling molecules such as NPY." (PMID 37373115, 2023). "Overexpression of ERG has been observed in several cancers, e.g., leukemia and Ewing’s sarcoma, and was also shown in approximately half of all prostate cancer patients." (PMID 37762215, 2023). "The role of ERG‐status molecular subtyping in prognosis of prostate cancer (PCa) is still under debate." (PMID 36329628, 2023). "In half of prostate cancers, ERG overexpression results from a 3Mb deletion, which fuses an androgen responsive promoter of TMPRSS2 to exon 4 of ERG." (PMID 37510283, 2023). "As far as ERG expression is concerned, we also observed an association with IDCP, a late event in prostate cancer progression." (PMID 37185705, 2023). "Further research is necessary to determine if a similar approach would change the ability of PABPC1 to promote ERG function in prostate cancer." (PMID 37956771, 2023). "Statistical analysis of PTEN and ERG expression in prostate carcinoma provided statistically significant results (p < 0.0001)." (PMID 37185705, 2023). "ERG is a transcription factor with diverse functions in endothelium and several malignancies including prostate cancer." (PMID 37310937, 2023). "As an oncogenic gene in prostate cancer, ERG regulates proliferation and invasion genes by orchestrating higher-order chromatin organization, which is distinct from AR-associated chromatin connectivity." (PMID 36997534, 2023). "The data from their study showed the substantial heterogeneity in PTEN aberrations in prostate cancer and advocates that ERG activation is a key driver of such abnormalities." (PMID 37185705, 2023). "The study highlights the fact that TMPRSS2:ERG fusion transcriptionally upregulates sGC; promoting cGMP synthesis in prostate cancer cells thus enhances cellular proliferation." (PMID 37511059, 2023). "The de-repression of AR target genes upon treatment with a pan-HDAC inhibitor was much more significant in ERG-positive prostate cancer cells than ERG-negative prostate cancer cells." (PMID 37735473, 2023).